CD151 (CD151 molecule (Raph blood group))
Diseases named in the same sentence as CD151 in open-access papers (continued):
Sharing a sentence is not in itself a finding about the gene and the disease.
tumor (continued). "The tumor-promoting role of CD151 may also be carried out through regulation of α3β1 integrin-dependent cell-ECM adhesion, migration, survival, and signaling." (PMID 33919420, 2021). "Further, knockdown of CD151 in vitro inhibited tumor proliferation, migration, and invasion." (PMID 34108040, 2021). "Hence, the impact of CD151 on cancer metastasis largely stems from regulation of tumor cell behaviors and survival, and their microenvironments." (PMID 33919420, 2021). "Similarly, when tumor cells were injected at a separate primary site, CD151-null mice also showed reduced lung metastasis and tumor cell residence." (PMID 32117989, 2020). "CD151 was the first tetraspanin to be identified as a tumor promoter." (PMID 32117989, 2020). "Here, we speculated that oncoprotein CD151 derived circRNAs might have certain roles in tumor promotion." (PMID 32381016, 2020). "CD151 ablation sensitized multiple tumor cell types to several anti-cancer drugs (e.g., gefitinib and camptothecin), thus increasing apoptosis, as seen using cleaved caspase-3, cleaved PARP (poly (ADP-ribose) polymerase), annexin V, and propidium iodide staining assays." (PMID 30778617, 2019). "CD151 may variably support tumor initiation, promotion, progression, metastasis, angiogenesis, and drug resistance." (PMID 30778617, 2019). "In addition, we proved CD151 as a potential tumor promoter in RCC by activating TGF-β1/Smad signaling and EMT, and playing a crucial role in RCC cells migration and invasion." (PMID 29568359, 2018). "The results of this study may reveal how CD151 acts as a tumor promoter in RCC cell lines and may provide a potential biomarker for the diagnosis, treatment and prognosis of RCC." (PMID 29568359, 2018). "To study the interactions among RNASEH2A, CDK1, and CD151 and their impact on tumor proliferation, we performed si-RNA knockdown studies on three ccRCC cell lines (786O, A704, KMRC3, all with VHL mutation) and one kidney urothelial carcinoma cell line (BFTC909, without VHL mutation)." (PMID 29843367, 2018). "Site-directed mutagenesis studies have revealed that CD151 could be palmitoylated at multiple sites, which is vital for the assemble of tumor endothelial marker (TEM) network." (PMID 27888619, 2017). "In addition to its role in cancer progression and metastasis, studies have shown that CD151 promotes tumor neovascularization and tumor growth." (PMID 27556355, 2016). "Additionally, a described role for CD151 was to recruit PKCα into proximity with the α6β4 integrin, which significantly impacted tumor initiation and progression." (PMID 27417454, 2016). "Interestingly, CD151 can promote MMP-9 expression in some tumor cells, and RNAi-mediated suppression of CD151 in epidermal carcinoma cells led to the internalization of α3β1 accompanied by down-regulation of MMP-9." (PMID 25751421, 2015). "Indeed, others have shown that CD151 promotes tumor growth and metastasis, and in some cases the CD151/α3β1 complex has been shown to regulate expression or proteolytic activity of certain MMPs." (PMID 25751421, 2015). "Thus, CD151- and Tspan8-competent tumor exosomes support matrix degradation, reprogram stroma and hematopoietic cells and drive non-metastatic ASML-CD151/Tspan8kd cells towards a motile phenotype." (PMID 25544774, 2015). "It is of no surprise that CD151 is frequently implicated in promoting tumor progression by enhancing either α3 or α6 integrin-dependent cellular processes." (PMID 26377974, 2015). "In addition, there are reports of links between CD151 expression and tumor grade or patient survival for several cancer types." (PMID 26377974, 2015). "Whilst the increase in tumor latency in Cd151−/− mice was only approaching significance, there was significant decrease in the number of tumors per mouse, suggesting that Cd151 deletion might impair PyMT tumor initiation." (PMID 25012362, 2014).
tumor (continued). "Similarly to the situation in the normal glands, CD151 appeared to be expressed strongly by the myoepithelial cell layer surrounding the tumor nodules of the early stage PyMT tumors, while the cancer cells in the nodules were only faintly labeled." (PMID 25012362, 2014). "In addition, a recent study showed that CD151 plays a role in mammary cell proliferation, suggesting the involvement of CD151 in tumor cell growth." (PMID 25012362, 2014). "Our results suggest that Cd151 deletion impairs tumor initiation and/or tumor growth in the MMTV/PyMT model, while an apparent effect on tumor metastasis could be attributable to larger tumor burden in Cd151+/+ mice." (PMID 25012362, 2014). "Interestingly both the total tumor weight (P = 0.0003) and tumor multiplicity (P = 0.0008) per mouse were significantly decreased in the Cd151−/− group as compared to Cd151+/+ group." (PMID 25012362, 2014). "Possible mechanisms for a role of CD151 overexpression in tumor progression may come from an enhancement of Rac and cdc42 activation and an effect of integrin-mediated tumor cell motility via FAK activation." (PMID 25285080, 2014). "The tetraspanin CD151 has also been tested as target of anti-tumor antibodies in animal models." (PMID 25285080, 2014). "Interestingly, the median age to tumor onset in the heterozygous Cd151+/− mice was in between the values reported for Cd151+/+ and Cd151−/− PyMT mice (Cd151+/− T50 = 63, n = 21)." (PMID 25012362, 2014). "Indeed, our analyses show that knocking down CD151 or α3 integrin enhances tumor cell proliferation, growth and ascites production in nude mice." (PMID 25356755, 2014). "Together our data shows that Cd151 deletion significantly impairs tumor occurrence and growth." (PMID 25012362, 2014). "CD9 is a potential tumor suppressor, while CD151 is supposed to promote tumor metastasis." (PMID 24995331, 2014). "In addition, clinical data revealed that elevated CD151 expression outperformed other commonly used clinical parameters such as increased tumor size and poor differentiation for predicting HGC prognosis." (PMID 23533596, 2013). "Furthermore, blocking of CD151 markedly impaired the invasiveness and metastatic potential of tumor cells, and targeting the CD151 protein or TEMs has become a promising therapeutic strategy." (PMID 23533596, 2013). "The postulated role of CD151 in cell migration and tumor spread led us to test if blocking CD151 expression or function could inhibit ovarian cell migration and invasion." (PMID 22272937, 2012). "A recent study also reported that CD151 has a role in proliferation of mammalian epithelial cells, suggesting that CD151 may contribute to the tumour cell growth." (PMID 22294188, 2012). "The Luminal A subtype had a lower incidence in tumours with CD151 expression." (PMID 22294188, 2012). "CD151 overexpression was found to be significantly associated with larger tumour size, higher nodal stage, advanced stage, absence of oestrogen receptor and progesterone receptor, and human epidermal growth factor receptor 2 overexpression." (PMID 22294188, 2012). "CD151 is a member of the mammalian tetraspanins, which are transmembrane proteins involved in a variety of biological processes including the immune system, fertilisation, infectious processes, and tumour progression." (PMID 22294188, 2012). "It is possible that the internalization of CD151 into cytoplasmic endosomes may reduce its ability to cooperate with other binding partners and cells, allowing detachment from the primary tumor." (PMID 22272937, 2012). "CD151 promotes tumor cell motility, invasion and metastasis of several clinical cancers." (PMID 22570691, 2012). "In addition, there have been several evidences supporting the contribution of CD151 in tumour progression." (PMID 22294188, 2012). "Additionally, anti-CD151 antibody treatment of high-CD151-expressing tumour cells decreased cell migration and metastasis." (PMID 22294188, 2012).
tumor (continued). "There was strong concordance (98%) of CD151 and E-cadherin staining, with only 1 of 43 tumours showing discordance in staining (i.e., cores positive for CD151 were positive for E-cadherin staining and cores negative for CD 151 were negative for E-cadherin staining)." (PMID 21505452, 2011). "As reported in our previous study, CD151 was mostly located on the membrane of tumor cells." (PMID 21961047, 2011). "We have hypothesised that those patients with a CD151-positive tumour are in a more advanced stage of the disease and have a much poorer prognosis." (PMID 12838318, 2003). "The ability of CD151 to mediate tumour cell migration may provide a possible mechanism for the role of this protein in effecting metastatic dissemination." (PMID 12838318, 2003). "Studies involving the transplantation of TSPAN8 and CD151 single- and double-knockout cancer cells into wild-type or autochthonous and syngeneic recipient mice have further unraveled the complex roles of these tetraspanins in host- versus tumor-derived exosomes." (PMID 38275818, 2024). "CD151 contributes to tumor metastasis and could be a potential anti-tumor target." (PMID 37192987, 2022). "As high CD151 levels predict high malignancy and low sorafenib sensitivity simultaneously, this underlines the substantial heterogeneity between high and low CD151 levels in HCC and the importance of assessing the molecular type of tumor when choosing a treatment regimen." (PMID 34540692, 2021). "Recently several findings suggested that CD151 may act as a core effector in many tumor cell types." (PMID 34108040, 2021). "In addition to its ability to regulate gene expression, α3β1 regulates several other tumor cell functions that are known to contribute to invasion and metastasis, including cell adhesion to laminins, interactions with the CD151 tetraspanin protein, and ECM proteolysis." (PMID 33513758, 2021). "Additionally, within the tetraspanin family, CD151 has long been regarded as a potent driver for cell adhesion and behaviors, and tumor onset, growth, angiogenesis and metastatic dissemination, and cancer relapse or resistance to current chemo- and targeted therapies." (PMID 33919420, 2021). "Thus, the close relationship between the tetraspanin family and tumor neoangiogenesis, CD151, and TSPAN8 may represent potential therapeutic targets of HCC in the future." (PMID 34540692, 2021). "Consequently, CD151 may guide the migratory activity of tumor cells to induce invasiveness and metastasis." (PMID 33980972, 2021). "However, it is unclear if the IPF phenotype observed in CD151-null mice is strain-specific as differences in renal function in tumor formation has been observed between FVB/N background [generated using 129SvEv ES cells] versus C57BL/6 mice [generated from 129/Ola and C57BL/6 ES cells]." (PMID 32117989, 2020). "In addition, it has been demonstrated that CD151, a member of the transmembrane 4 superfamily, induced skin chemical carcinogenesis and promoted the development of SCC, because CD151 might induce the activator of transcription 3 (STAT3)." (PMID 29301290, 2018). "Consequently, we suggest that the aberrant expression of CD151 could act as a tumor promoter and therapeutic target for treating RCC." (PMID 29568359, 2018). "The tetraspanin CD151, primarily identified as a molecular organizer of interacting proteins (integrins, growth factors, MMPs) into tetraspanin-enriched microdomains, is also involved in tumor progression and is thus being seriously considered as a potential anticancer target." (PMID 28752248, 2017). "In addition, CD151 is regarded as a potential therapeutic target based on its role in promoting tumor progression, and several groups have proposed and developed antibody-based immunotherapies against CD151 while others have reported soluble large-loop proteins or RNAi technology to inhibit CD151." (PMID 27556355, 2016).
tumor (continued). "Moreover, a small subset of cells isolated from the CWR22 orthotopic tumor xenograft model display TRA-1-60, CD166 and CD151 markers, with TRA-1-60+CD166+CD151+ cells initiating tumor formation in vivo at increased efficiency following serial dilution of cells compared to TRA-1-60+ cells." (PMID 25595909, 2015). "As tetraspanins are constitutive exosome components and known to be engaged in exosome binding and uptake, we speculated that the metastasis-promoting tetraspanins CD151 and Tspan8 could play a central role in the process of tumor exosome-mediated host modulation." (PMID 25544774, 2015). "Surprisingly, several CD9/CD81 functions, including promoting α3β1's association with PKCα and promoting α3β1-dependent tumor cell migration on LM-332, may not require CD151-dependent complex formation with α3β1 in this system." (PMID 23613949, 2013). "Clinically, CD151 overexpression was significantly correlated with high TNM stage, depth of invasion and positive lymph node involvement (p<0.05), and high levels of integrin α3 were associated with large tumor size, high TNM stage, depth of invasion and lymph node involvement (p<0.05)." (PMID 23533596, 2013). "The cell adhesion molecule binding cluster in TuNEPs contained tumorigenic proteins such as ITGA2, CD151, CD9, SLC3A2, and BSG, all known to have an impact on the tumor microenvironment." (PMID 40751052, 2025). "CD9, CD151, TSPAN1, TSPAN3, TSPAN8, and TSPAN13 displayed specific overexpression in the tumor compartment, indicating potential roles in tumor growth." (PMID 38255741, 2024). "Differential expression and survival analyses of CD151 in TCGA-LIHC, ICGC-LIRI, and GSE14520 affirmed its elevated expression in tumour samples with a corresponding correlation to poor prognosis." (PMID 38840183, 2024). "For instance, CD151 and TSPAN8, which have been proposed as potential therapeutic targets for CC, were overexpressed in the tumor region of stage 4 primary CC tumors." (PMID 38255741, 2024). "The tetraspanins CD151 and TSPAN8 support metastatic tumor growth and metastatic niche formation in the lung and bone marrow." (PMID 38954230, 2024). "The functional similarities shared by CD151 and TSPAN4, both belonging to the four-transmembrane protein family, elucidate CD151’s comparable labelling effect in tumour cells, where its expression significantly surpasses that of TSPAN4 in pan-cancer contexts." (PMID 38840183, 2024). "In the tumor compartment, several tetraspanins (CD9, CD151, TSPAN1, TSPAN3, TSPAN8, and TSPAN13) were specifically overexpressed, suggesting their involvement in tumor growth and proliferation in stage 4 primary CC." (PMID 38255741, 2024). "In addition, the results indirectly indicate that, despite the low representation of the CD151+Tspan8+ subpopulation (about 3%) of exosomes, it is they that contribute to the transfer of signals from cancer cells to recipient cells and thus, to tumor dissemination itself." (PMID 36613908, 2022). "Two tetraspanins, CD151 and tetraspanin 8 (also known as CO-029 and TM4SF3 in human, and D6.1A in rats), are upregulated in PDAC and support tumour progression." (PMID 34671031, 2021). "These candidate markers (CLDN4, EPCAM, CD151, LGALS3BP, HIST2H2BE, and HIST2H2BF) effectively isolated tumor-derived EVs in clinical samples." (PMID 34948417, 2021). "In case of CD151, it is suggested to act in concert with TSPAN8 to drive exosome production in both tumor and endothelial cells, thereby facilitating tumor metastasis." (PMID 33919420, 2021). "To date, many tumor metastasis- and invasion-related studies have focused on CD9, CD81, CD82/KAI1, CD151, and TM4SF1." (PMID 30876464, 2019). "Several proteins already known to promote tumor metastasis (NOTCH2, NCS1, NUSAP1, CD151), were increased more than 10-fold under hypoxic conditions, further demonstrating the potent effects of oxygen restriction on cancer cell biology." (PMID 31666928, 2019).
tumor (continued). "Besides, it could promote target gene CD151 to induce tumor cell migration and angiogenesis." (PMID 31126066, 2019). "In HCC cell lines QGY- 7703 and SMMC-7721, and normal hepatic cell line HL-7702, miR-124 plays a tumor suppressor role by targeting PIK3C2A and CD151." (PMID 27270320, 2016). "These experiments illustrated that miR-124 plays a tumor suppressor role in HCC cells by targeting PIK3C2A and CD151." (PMID 27270320, 2016). "The second substrate of ZDHHC2 related to its putative tumor/metastasis suppressor is tetraspanins CD9 and CD151." (PMID 23457560, 2013). "In relation to tumour metastasis, experiments using anti-CD151 mAb have established that this tetraspanin may contribute to an early step in the formation of secondary metastatic lesions by mediating invasiveness of primary tumour cells into surrounding stromal tissues and vascular intravasation." (PMID 21505452, 2011). "HCC characterized by microvascular invasion, large tumor (>5 cm) size, and high TNM stage, were prone to higher expression of the CD151/integrin β1 complex." (PMID 21961047, 2011). "Furthermore, it was shown that CD151 is essential for OC cell survival through a ZEB-dependent mechanism and supports tumor development, so high CD151 expression in tissue is prognostic of poor clinical outcome." (PMID 36613908, 2022). "High expression of CD151 leads to amplification of the integrin α6β1-PI3K signal in HCC and may therefore increase the aggressiveness of tumor aggressiveness." (PMID 36010583, 2022). "Additionally, while it appears that the role of CD9 in promoting or inhibiting tumor progression is rather controversial, CD151 and TSPAN8 are believed to be involved in tumor progression, displaying rather oncogenic properties." (PMID 34830819, 2021). "Over the past decade, CD151 is increasingly appreciated as a functionally versatile molecule and driver of human epithelial-origin cancers whereby it regulates cell-cell junctions, proliferation, EMT, metabolism and CSCs, as well as tumor microenvironments." (PMID 33919420, 2021). "In addition, CD151 silencing was shown to suppress cell migration and invasion in cultured CRC cells in vitro, and reduce tumor growth in mouse xenograft models." (PMID 33767593, 2021). "Interestingly these impaired phenomena in knockout mice can be mitigated by Tspan8/CD151-competent serum exosomes, through stimulating GPCR and RTK-dependent angiogenesis which ultimately contribute to tumour progression in vivo." (PMID 34671031, 2021). "Interestingly, increased RNASEH2A and CD151 expression was observed in si-CDK1-treated ccRCC cell lines and were was found in RCC patients with a low tumor CDK1 level and bad clinical outcomes." (PMID 29843367, 2018). "CDK1 knockdown resulted in the upregulation of RNASEH2A and CD151 in all cell lines, however it did not significantly impair tumor proliferation (except for a mild effect on A704)." (PMID 29843367, 2018). "CD151 protein expression was detected in 30 pairs of HCC tumor and nontumor samples using immunohistochemical staining with CD151 mAb 9B." (PMID 26756217, 2016). "Our data showed that patients belonging to the CD151-high group had poorer survival than their counterparts, regardless of how patient samples were pooled by tumor grade." (PMID 26377974, 2015). "Though these activities are generally fitting a contribution to tumor progression, only CD151 and Tspan8 were described as metastasis-promoting in several tumor systems, with no opposing findings reported so far." (PMID 25544774, 2015). "Our co-immunoprecipitation analyses with [3H]-palmitate-labeled tumor cells indicate that a number of proteins, including CD9 and CD81, were no longer associated with α3β1 integrin in the absence of CD151." (PMID 25356755, 2014). "However, CD63 was excluded from the membrane surface, where it plays a tumor-suppressive role, by the expression of TM4SF5 and/or CD151." (PMID 25033048, 2014).